ATXN7L2 (ataxin 7 like 2)
Synonyms: MGC46534; FLJ00381
Tractability: PROTAC: ubiquitination databases record sites on it.
Gene: Protein-coding gene on chromosome 1 (109,483,479 to 109,492,812, forward strand). Ensembl gene ENSG00000162650.
Subcellular location (Human Protein Atlas): Nucleoli rim; Cytosol; Vesicles
Genetic constraint (gnomAD): Loss-of-function variants: 17 observed, 56.28 expected, observed/expected ratio (o/e) 0.3, 90% interval 0.21 to 0.45. The upper end of that interval is the gene's LOEUF score, 0.45, which puts it in group 2 of 6, group 1 being the genes least tolerant of losing a copy. Missense variants: 858 observed, 1,001.5 expected, observed/expected ratio (o/e) 0.86, 90% interval 0.81 to 0.91. Synonymous variants: 378 observed, 391.94 expected, observed/expected ratio (o/e) 0.96, 90% interval 0.89 to 1.05.
Homologues: Orthologues: macaque ATXN7L2 (98% identical), chimpanzee ATXN7L2 (94% identical), dog ATXN7L2 (93% identical), pig ATXN7L2 (91% identical), rabbit ATXN7L2 (89% identical), guinea pig ATXN7L2 (85% identical), rat Atxn7l2 (84% identical), mouse Atxn7l2 (82% identical), zebrafish atxn7l2a (31% identical), zebrafish atxn7l2b (28% identical). Paralogues in human: ATXN7L1 (31% identical), ATXN7 (30% identical), ATXN7L3 (11% identical), ATXN7L3B (2% identical).
Diseases named in the same sentence as ATXN7L2 in open-access papers:
ATXN7L2 is named in the same sentence as 2 diseases in open-access papers, as found by Europe PMC text mining. Sharing a sentence is not in itself a finding about the gene and the disease. The quoted sentences say what the papers report.
non-small cell lung carcinoma (1 paper, 2020). A group of at least three distinct histological types of lung cancer, including non-small cell squamous cell carcinoma, adenocarcinoma, and large cell carcinoma. "A similar situation applies to ATXN7L2; there is only one publication in PubMed suggesting its biomarker potential in non-small cell lung cancer." (PMID 33266355, 2020).
ATXN7L2 also shares sentences with these, for which no sentence is quoted: tumor (1 paper).